ID1 (inhibitor of DNA binding 1)
Diseases named in the same sentence as ID1 in open-access papers (continued):
Sharing a sentence is not in itself a finding about the gene and the disease.
tumor (continued). "Primary ESCC tumours with more than 11.86% (mean percentage of nuclei stained positive in ESCC specimens) of nuclei stained positive for Id-1 were regarded as having high and others as having low nuclear expression." (PMID 18000500, 2007). "In conclusion, this work describes for the first time the opposing activity of two regulators of the differentiation of BM-derived EPCs from BM stem cells, Id1 and p21, and supports the importance of these cells during tumor angiogenesis." (PMID 18092003, 2007). "We observed that primary tumours at M1 stage had a significantly higher nuclear Id-1 expression than M0 stage tumours (P=0.012)." (PMID 18000500, 2007). "It is well established that various members of the Id family are overexpressed in a range of human tumours and generally, Id1 appears to be the family member most widely overexpressed in a variety of human malignancies, including multiple myeloma." (PMID 15877825, 2005). "In further analysis of subgroups with higher and lower Id-1 expression, tumours with higher Id-1 expression (scores 4 and 5) showed significantly higher MVD than tumours with lower expression of Id-1 (scores 2 and 3) (111.18±57.14 vs 64.13±28.19, P<0.001)." (PMID 15026801, 2004). "It has been suggested that Id-1 has a critical role in the tumour progression and aggressiveness of several human cancers." (PMID 15026801, 2004). "To investigate the association between Id-1 expression and cell proliferation or tumour angiogenesis, we examined PI, AI and MVD in tumour cells using Ki-67, TUNNEL and CD34 staining, respectively." (PMID 15026801, 2004). "In summary, we speculate that BYJHD exerts its anti-NSCLC activity through the ACVRL-1/Smad/ID-1 axis and the inhibition of CD expression, thereby regulating the tumour microenvironment and inhibiting tumour angiogenesis." (PMID 41579221, 2026). "For instance, CBD downregulates Id-1, a key regulator of tumor aggressiveness, in MDA-MB-231 cells." (PMID 40275168, 2025). "Indeed, ID1/2 play a role in tumour progression by enhancing cancer stem cell renewal, metastatic dissemination and proliferation." (PMID 40280979, 2025). "While the upregulation of DKK3 and ALDOC enhanced differentiation, the downregulation of ID1 may reduce the oncogenic potential, reinforcing the tumor-suppressive effects of the treatment." (PMID 40753072, 2025). "Results herein support existing data of ID1 regulating IL‐8, a pro‐inflammatory cytokine that is constitutively expressed by many tumour cells to attract and modulate neutrophils, mediate cell metastasis, enhance vascular permeability, and promote VM formation." (PMID 40116596, 2025). "Neither TGF-B1, BMP4 and GREM1 transcript levels nor ID1 and pSMAD2 protein expression were significantly associated with survival in either tumour or stromal compartments." (PMID 40826447, 2025). "In conclusion, ID1 is a critical target for inhibiting tumor angiogenesis in TNBC." (PMID 40820992, 2025). "High expression levels of ID1 in various tumor tissues indicate its oncogenic properties." (PMID 40820992, 2025). "It further confirmed that ID1 is a key target for anti-tumor." (PMID 40820992, 2025). "Protein overexpression of ID1 has been described as a negative prognostic predictor associated with higher tumour (T)- and nodal (N)-stage as well as higher microvessel density in PDAC." (PMID 40826447, 2025). "On the one hand, it inhibits tumor angiogenesis through the ID1/TSP-1 pathway." (PMID 40820992, 2025). "Interestingly, while hypoxic regions were observed only in the core of control tumors, ID1-overexpressing tumors exhibited hypoxic regions throughout the tumor." (PMID 38658527, 2024).
tumor (continued). "Moreover, we found that Id1 plays a major role in the acquired resistance to trametinib treatment in KRAS-mutant LUAD tumor cells." (PMID 38643157, 2024). "In addition to controlling the intrinsic properties of the tumour, there is increasing evidence that ID1 participates in the formation of an immunosuppressive microenvironment." (PMID 39676870, 2024). "Furthermore, ID1 expression was decreased in the mice tumor tissues subjected to usenamine A treatment compared to that of the controls." (PMID 38183094, 2024). "ID1 overexpression contributes to invasion and tumor progression." (PMID 38195969, 2024). "Additionally, jozimine A2 does not only prevent translocation of NF-κB to the nucleus, but it also blocks tumor-progression genes such as ID1 and VEGF." (PMID 38542061, 2024). "Additionally, Id1 and Id3 also play a role in the tumour immune microenvironment by supporting cancer cell stemness, limiting CD8+ T cell responses, and promoting an immunosuppressive environment." (PMID 39676870, 2024). "Interestingly, we have also demonstrated how a MEK1/2 inhibitor can modulate the immunosuppressive tumor microenvironment of KRAS-mutant lung adenocarcinoma (LUAD) tumors though Id1 downregulation (unpublished data)." (PMID 37841258, 2023). "Notably, iCAFs marked by TPM2 were enriched in the initial differentiation phase while myCAFs characterized by BIRC3, CCT6A, HNRNPF, and ID1 were enriched in the terminal differentiation phase during tumor progression." (PMID 37968457, 2023). "Moreover, Id1 has been described as an immunosuppressor factor involved in the generation of an immunosuppressive tumor microenvironment during tumor progression." (PMID 37841258, 2023). "In addition to controlling tumor intrinsic properties, growing evidence indicates that ID1 is involved in the formation of an immunosuppressive microenvironment mediated by myeloid-derived suppressor cells (MDSCs) to promote melanoma progression." (PMID 37996458, 2023). "Interestingly, ID1 expression leads to IL-6 production, activating STAT3, which is known to drive tumor associated macrophages toward an immunosuppressive phenotype, also promoting angiogenesis, invasion and epithelial-mesenchymal transition (EMT)." (PMID 38028629, 2023). "Although no tumor-associated mutations were observed in the ID1 gene, it is still considered as a cancer-promoting factor." (PMID 37996458, 2023). "In order to explore the clinical relevance of Id1 depletion at the tumor microenvironment, we analyzed immune populations in tumors from mice responding to anti-PD-1 therapy (in Id1-silenced host microenvironment) and non-responding mice (mice with constitutive Id1 expression)." (PMID 37841258, 2023). "We further investigated whether ID1 ablation in macrophages inhibited tumor progression using two TAM adoptive transfer models." (PMID 37996458, 2023). "However, new evidence has emerged, linking ID1 to suppression of the anti-tumor immune response in the myeloid compartment and promoting tumor progression." (PMID 38127790, 2023). "Conversely, ID1 inhibition results in a decrease in tumor growth and metastasis." (PMID 37759448, 2023). "Essentially, the lungs of tumor-bearing mice demonstrated higher levels of Id1." (PMID 35955525, 2022). "ID1 is mainly correlated with tumorigenesis, cell senescence, cell proliferation, and survival, and is overexpressed in various cancer cells and can promote tumor development through different signaling pathways." (PMID 36232998, 2022). "In the TCGA (The Cancer Genome Atlas Program) dataset, tumor tissues from different PDAC patients showed different ID1 expression levels, and patients with high ID1 expression had significant lower overall survival years compared to those with lower ID1 expression." (PMID 35941362, 2022). "A previous study demonstrated that ID1 promotes tumor invasiveness and migration." (PMID 35805116, 2022).
tumor (continued). "Therefore, noggin is understood to be tumour‐promoting through its reduction in ID1 expression, while BMP‐9 is understood to be tumour‐suppressive in how it shifts the ID1/NOG ratio in a favourable direction." (PMID 34841646, 2022). "Specifically, we found that genes involved in regulation of cell lineage transition and tumor progression including inhibitor of differentiation 1 (ID1), actin cytoskeletal regulator PFN2 and ID334–39 are among the top of the upregulated genes in ENZ-R cells compared to control cells." (PMID 33750801, 2021). "Research on the pulmonary vascular cell model (microvascular endothelial cell line: HMEC-1) showed that TMP could suppress angiogenesis and tumor growth in lung cancer by blocking the BMP/Smad/Id-1 signaling pathway in a dose- and time-dependent manner." (PMID 34975475, 2021). "Treatment with LDN‐212854 suppressed HCC tumor growth by repressing ID1 and EpCAM in vivo." (PMID 33834612, 2021). "This places ID1 downstream of Nur77 in tumor growth control." (PMID 33990575, 2021). "However, forced expression of Id1 did not enhance tumorsphere formation, size of side population (SP) fraction or tumor formation in vivo, suggesting that Id1 acts upon the progenitor proliferating population rather than on stem or cancer stem cells." (PMID 34736527, 2021). "In an environment of low TGFβ signal, Nur77 acts as a tumor suppressor by reducing ID1 expression." (PMID 33990575, 2021). "We found that ID1 knockout inhibited tumor growth, signifying the pro-tumorigenic effect of ID1." (PMID 33990575, 2021). "By performing differentially expressed gene (DEG) analysis, we found that many immunosuppressive and exhaustion-related genes such as LAG3, CD101, SMAD2, and ID1, which was one type of the mediators of tumor progression, were highly expressed in PBMCs from RTP patients." (PMID 34687295, 2021). "These genes are known to be key developmental regulators intensively associated with tumor progression and ID1 is a negative prognostic marker for ccRCC." (PMID 34638458, 2021). "We used the Id1C3-Tag tumor model as a second murine model to assess the phenotype of Id1+ cells." (PMID 32766238, 2020). "Interestingly, we found that there was a significant enrichment for Id1+ tumor cells after treatment with paclitaxel and doxorubicin, suggesting that the Id1+ CSCs are chemoresistant." (PMID 32911668, 2020). "Interestingly a significant increase in TIL was observed specifically in mice with the combined inhibition of Id1 in both tumor cells and tumor microenvironment and PD-1." (PMID 33126649, 2020). "However, the analysis of the number of CD8+ and CD4+ T cells showed the highest tumor infiltration by both types of lymphocytes in Id1 knockout mice bearing Id1-silenced tumor cells treated with anti-PD-1 therapy." (PMID 33126649, 2020). "To better understand the molecular mechanisms underlying in the Id1-loss phenotype in combination with the blockade of the PD-1/PD-L1 axis, we investigated the potential role of each immune cell subpopulation in the observed antitumor effect on the tumor growth when both Id1 and PD-1 were inhibited." (PMID 33126649, 2020). "We hypothesized that targeting Kif11 or Aurka to block the Id1-Kif11/Aurka axis may cause the Id-expressing CSC to be more vulnerable to chemotherapy and more effectively debulk the entire tumor mass." (PMID 32911668, 2020).
tumor (continued). "The multivariate Cox proportional hazards model revealed that tumor size, number of tumor nodules, and Id-1 and CCN2 expression were also independent prognostic indicators for OS and CCR of HCC patients; however, vascular invasion was an independent prognostic indicator for OS in HCC patients." (PMID 31250351, 2019). "This study has identified ID1 as the top upregulated gene in R1 cell-derived tumor xenograft." (PMID 31013771, 2019). "We identified ID1 as the top upregulated gene in the tumor generated by 5-FU resistant cells." (PMID 31013771, 2019). "We identified Id1 as the pivotal respondent to baicalein in its anti-tumor effect." (PMID 30949224, 2019). "In conclusion, our data demonstrated the antitumor effect of baicalein in orthotopic NSCLC model for the first time and clarified that Src/Id1 pathway was involved in the baicalein-induced inhibition of tumor growth, providing further insight into the therapeutic strategies." (PMID 30949224, 2019). "Similar to VEGF, Id1 has been shown to enhance tumor angiogenesis and microvessel density." (PMID 31100813, 2019). "The in vivo subcutaneous tumor growth capacity of MHCC-97H cells transfected with Id-1 shRNA in nude mouse models was significantly diminished, whereas it is significantly enhanced when the Id-1 was upregulated through lentiviral transfection in MHCC-97H cells." (PMID 31250351, 2019). "The tumor volume was higher in ID1-knockdown group, indicating resistance to sorafenib." (PMID 30154433, 2018). "The ID proteins have been implicated in many processes involved in oncogenesis, and importantly, ID1 was shown to be upregulated by TGF-β in tumor cells isolated from pathological pleural fluids from patients with ER− and ER+ metastatic breast cancer, and also in patient-derived glioblastomas." (PMID 29376829, 2018). "Id1/Id3 expression promotes stemness properties and tumor initiation." (PMID 30297743, 2018). "Moreover, Id1 and Id3 endow tumor cells with stemness properties, thereby contributing to cancer initiation in vivo." (PMID 30297743, 2018). "BMP-2 upregulation of target gene ID-1 (which activates pathways involved in tumour progression) may contribute to this effect." (PMID 28733469, 2017). "ID1 and ID3 associated with the tumor promotion and metastasis." (PMID 28785583, 2017). "TGFβ-induced overexpression of Id1 is necessary not only to obtain tumor-initiating cells at the primary site, but also to switch the EMT phenotype, which is induced by the zinc finger transcription factor Snail at the primary site, back to the MET one at the colonization site." (PMID 28122577, 2017). "This shows that Id1 plays a role in tumor-induced immunosuppression." (PMID 28122577, 2017). "An analogue of dorsomorphin (DMH1), much more highly selective for type 1 BMPR, can attenuate the pro-tumour microenvironment by altering the expression of certain genes (such as ID-1 and matrix metalloproteases-MMPs) in fibroblasts, lymphatic vessels and macrophages in a mouse model." (PMID 28733469, 2017). "It has been proposed that in androgen-dependent prostate cancers androgen might regulate proliferation, apoptosis and tumor suppression via Id1/Id3, Id2 and Id4 regulation, respectively." (PMID 28122577, 2017). "ALK1-induced expression of ID1 promotes tumor cell metastasis." (PMID 28445989, 2017). "Knowing that ID1/G6PD signaling promoted tumor cell proliferation and chemoresistance in HCC, we wondered whether ID1/G6PD signaling could predict unfavourable prognosis in HCC patients." (PMID 29169374, 2017). "Our in vivo data substantiate that through this mechanism, Id1-expressing ESCC tumours can indirectly promote the functional incorporation of VEGFR1+ bone marrow cells into primary tumours and secondary sites to facilitate tumour growth and formation of pre-metastatic niche." (PMID 28186102, 2017).
tumor (continued). "In contrast, lack of this regulation in androgen-independent cancers might lead to cell proliferation (Id1 and Id3 up-regulation), cell survival (Id2 down-regulation) and decreased tumor suppression (Id4 down-regulation)." (PMID 28122577, 2017). "The preponderance of VEGFR1+ BMDCs in the growing tumours and the lungs of the Id1 group prompted us to explore whether inhibiting the activity of these cells by VEGFR1 inactivation could suppress tumour growth and metastasis." (PMID 28186102, 2017). "Moreover, blocking the NF-κB pathway significantly inhibited the tumor-promoting actions of Id-1 in NSCLC cells." (PMID 29233161, 2017). "Altogether, these data suggest that simultaneous high expression of ID1, ID3 and IGJ could be associated with poor prognosis in Hispanic adult B-ALL due to its potential to increase tumor cell survival possibly through NF-kB signaling." (PMID 27044543, 2016). "Thus it appears that Id1 expression is critical for angiogenic processes found in the tumor microenvironment or the RA joint, further suggesting that dysregulation of Id1 can lead to unwanted inflammatory outcomes." (PMID 27071670, 2016). "The expression of Id1 is necessary for Ras induced tumor formation by inhibiting senescence." (PMID 27048361, 2016). "We found that, similar to defects seen in tumour-bearing mice, Id1-overexpressing mice exhibited a decrease in splenic DCs (1.5-fold) and an increase in MDSCs (2.7-fold) compared with control vector mice, with both granulocytic and monocytic populations being equally affected." (PMID 25924227, 2015). "Similarly to Id1, Id3 expression was higher in DCs from tumour-bearing mice compared to DCs from control mice, however, Id3 expression levels in MDSCs from tumour-bearing mice were significantly lower compared to MDSCs from non-tumour-bearing mice." (PMID 25924227, 2015). "This raises the possibility that Id1 and Id3 compensate for the function of Id2 in the duodenal- and jejunal-tumor initiation that is not affected by the loss of Id2." (PMID 26163528, 2015). "A more recent study has also shown that loss of Id1 inhibits tumor initiation but does not affect tumor expansion in ApcMin/+ mice." (PMID 26163528, 2015). "Here we demonstrate that upregulation of the Inhibitor of Differentiation 1 (Id1), in response to tumour-derived factors, such as TGFβ, is responsible for the switch from dendritic cell (DC) differentiation to myeloid-derived suppressor cell expansion during tumour progression." (PMID 25924227, 2015). "Indeed immunohistochemistry results demonstrate that emergent lung metastases also express abundant levels of nuclear Id1 in a subset of tumour cells within these lesions." (PMID 25598217, 2015). "Notably, after receiving the adjuvant chemotherapy the patients with high Id1 expression in tumor tissues showed a better disease-free survival and overall survival than those with low Id1 expression by Kaplan-Meier survival analysis." (PMID 25344919, 2014). "Id1 and Id3 are highly expressed in endothelial cells in both developing and tumor blood vessels." (PMID 24516656, 2014). "In our clinical analysis, the size of primary tumor of NSCLC patients with high Id1 expression was in average larger than that of the patients with low Id1 expression before the definitive adjuvant chemotherapy, implying that Id1 acted as a negative prognostic factor in NSCLC." (PMID 25344919, 2014). "Moreover, high Id1 expression levels are correlated with aggressive and high-grade cancer, as well as poor clinical outcome in different tumor types." (PMID 24970809, 2014). "In addition, the NSCLC patients with high Id1 expression in primary tumor tissues had a better survival rate than the patients with low Id1 expression after surgical resection followed by the definitive chemotherapy." (PMID 25344919, 2014). "In summary, GCIP is a tumor suppressor that interacts with Id1 in NSCLC." (PMID 24970809, 2014).